WRN (WRN RecQ like helicase)
Description:
Multifunctional enzyme that has magnesium and ATP-dependent 3'-5' DNA-helicase activity on partially duplex substrates. Also has 3'->5' exonuclease activity towards double-stranded (ds)DNA with a 5'-overhang. Has no nuclease activity towards single-stranded (ss)DNA or blunt-ended dsDNA. Helicase activity is most efficient with (d)ATP, but (d)CTP will substitute with reduced efficiency; strand displacement is enhanced by single-strand binding-protein (heterotrimeric replication protein A complex, RPA1, RPA2, RPA3). Binds preferentially to DNA substrates containing alternate secondary structures, such as replication forks and Holliday junctions. May play an important role in the dissociation of joint DNA molecules that can arise as products of homologous recombination, at stalled replication forks or during DNA repair. Alleviates stalling of DNA polymerases at the site of DNA lesions. Plays a role in the formation of DNA replication focal centers; stably associates with foci elements generating binding sites for RP-A (By similarity). Plays a role in double-strand break repair after gamma-irradiation. Unwinds some G-quadruplex DNA (d(CGG)n tracts); unwinding seems to occur in both 5'-3' and 3'-5' direction and requires a short single-stranded tail. d(CGG)n tracts have a propensity to assemble into tetraplex structures; other G-rich substrates from a telomeric or IgG switch sequence are not unwound. Depletion leads to chromosomal breaks and genome instability.
Synonyms: RECQ3; RECQL2; RECQL3
Tractability: Small molecule: a structure with a bound ligand is known; a high-quality ligand is known. PROTAC: UniProt records ubiquitination sites on it; ubiquitination databases record sites on it; its protein half-life has been measured; a small molecule that binds it is known.
Target class: Enzyme; Hydrolase
Chemical probes: HRO761 (high quality)
Gene: Protein-coding gene on chromosome 8 (31,033,779 to 31,176,138, forward strand). Ensembl gene ENSG00000165392.
Subcellular location: Nucleus, nucleolus; Nucleus; Nucleus, nucleoplasm; Chromosome
Subcellular location (Human Protein Atlas): Nuclear speckles
Pathways (Reactome):
DNA Repair: HDR through Homologous Recombination (HRR); HDR through Single Strand Annealing (SSA); Homologous DNA Pairing and Strand Exchange; Presynaptic phase of homologous DNA pairing and strand exchange; Processing of DNA double-strand break ends; Resolution of D-loop Structures through Holliday Junction Intermediates; Resolution of D-loop Structures through Synthesis-Dependent Strand Annealing (SDSA)
Disease: Defective HDR through Homologous Recombination Repair (HRR) due to PALB2 loss of BRCA1 binding function; Defective HDR through Homologous Recombination Repair (HRR) due to PALB2 loss of BRCA2/RAD51/RAD51C binding function; Defective homologous recombination repair (HRR) due to BRCA1 loss of function; Impaired BRCA2 binding to PALB2; Impaired BRCA2 binding to RAD51
Cell Cycle: G2/M DNA damage checkpoint; Processive synthesis on the C-strand of the telomere; Removal of the Flap Intermediate from the C-strand
Metabolism of proteins: SUMOylation of DNA damage response and repair proteins
Gene Ontology:
Molecular function: 3'-5' DNA helicase activity; 3'-5' exonuclease activity; 3'-flap-structured DNA binding; 8-hydroxy-2'-deoxyguanosine DNA binding; ATP hydrolysis activity; bubble DNA binding; DNA binding; DNA helicase activity; exonuclease activity; forked DNA-dependent helicase activity; four-way junction DNA binding; four-way junction helicase activity; G-quadruplex DNA binding; magnesium ion binding; manganese ion binding; MutLalpha complex binding; protein binding; protein homodimerization activity; protein-containing complex binding; telomeric D-loop binding; telomeric G-quadruplex DNA binding; Y-form DNA binding; ATP binding; catalytic activity, acting on DNA; helicase activity; and 2 more
Biological process: base-excision repair; cellular response to gamma radiation; cellular response to starvation; cellular senescence; DNA damage response; DNA geometric change; DNA metabolic process; DNA replication; DNA synthesis involved in DNA repair; double-strand break repair; mismatch repair; positive regulation of strand invasion; protein localization to nucleolus; replication fork processing; response to UV-C; telomere maintenance; telomeric D-loop disassembly; t-circle formation; telomere maintenance via semi-conservative replication; DNA recombination; DNA repair
Cellular component: centrosome; chromosome; chromosome, telomeric region; nuclear speck; nucleolus; nucleoplasm; nucleus; cytoplasm; replication fork
Genetic constraint (gnomAD): Loss-of-function variants: 129 observed, 165.92 expected, observed/expected ratio (o/e) 0.78, 90% interval 0.67 to 0.9. The upper end of that interval is the gene's LOEUF score, 0.9, which puts it in group 3 of 6, group 1 being the genes least tolerant of losing a copy. Missense variants: 1,556 observed, 1,667.2 expected, observed/expected ratio (o/e) 0.93, 90% interval 0.89 to 0.97. Synonymous variants: 516 observed, 562.66 expected, observed/expected ratio (o/e) 0.92, 90% interval 0.85 to 0.99.
Gene-disease validity (ClinGen):
ClinGen rates the evidence that WRN causes each of these diseases.
Werner syndrome (autosomal recessive): Definitive.
Homologues: Orthologues: chimpanzee WRN (98% identical), macaque WRN (94% identical), pig WRN (76% identical), dog WRN (75% identical), guinea pig WRN (73% identical), rabbit WRN (72% identical), mouse Wrn (70% identical), rat Wrn (69% identical), tropical clawed frog wrn (52% identical), zebrafish wrn (44% identical), Caenorhabditis elegans wrn-1 (22% identical). Paralogues in human: BLM (18% identical), RECQL5 (14% identical), RECQL4 (13% identical), RECQL (12% identical).
Diseases named in the same sentence as WRN in open-access papers:
WRN is named in the same sentence as 138 diseases in open-access papers, as found by Europe PMC text mining. Sharing a sentence is not in itself a finding about the gene and the disease. The quoted sentences say what the papers report.
Werner syndrome (245 papers, 2006 to 2026). "WRN promotes genome stability through its functions in DNA replication, repair and telomere maintenance, the deficiency of which presents clinically as Werner syndrome, causing premature aging and cancer predisposition." (PMID 42129166, 2026). "Werner syndrome (WS) is caused by homozygous or compound heterozygous loss-of-function mutations in the WRN gene, with over 70 different pathogenic variants identified, inherited in an autosomal recessive pattern." (PMID 41511357, 2026). "In Werner syndrome patients, WRN deficiency leads to impaired transcription of the enzyme, resulting in NAD+ depletion, which leads to accelerated aging." (PMID 39759116, 2025). "For instance, mutations in the Werner syndrome ATP‐dependent helicase (WRN) gene, responsible for Werner syndrome, accelerate aging and manifest as premature skin aging." (PMID 39604792, 2025). "The accelerated aging disease Werner syndrome (WS) is a segmental progeria caused by mutations in the gene encoding the RecQ DNA helicase WERNER (WRN) protein." (PMID 40179319, 2025). "Mutations in WRN lead to Werner syndrome, a type of autosomal recessive disorder being recognized as premature senility." (PMID 39759116, 2025). "A similar phenotype is observed in Werner syndrome (WS), where mutations in the WRN helicase drive premature HSC depletion and cellular senescence." (PMID 41302153, 2025). "Pathogenic or null mutations in WRN helicase is a cause of premature aging disease Werner syndrome (WS)." (PMID 39863890, 2025). "Human Werner syndrome (adult progeria, a well-established model of human aging) is caused by mutations in the Werner syndrome (WRN) gene." (PMID 40261911, 2025). "Studies of cultured cells from patients with Werner syndrome and in animal models harboring WRN mutations have shown that WRN plays roles in DNA replication, DNA damage repair, transcription, and recombination as well as telomere maintenance." (PMID 40261911, 2025). "Given that WRN mutations cause Werner syndrome—a condition characterized by premature aging—we anticipated that WRN expression would decrease with age." (PMID 40261911, 2025). "The patient was initially diagnosed with secondary small fiber sensory polyneuropathy and myotonia, but further genetic testing revealed the homozygous pathogenic variant c.1578del in the WRN gene associated with Werner syndrome." (PMID 40060251, 2024). "The gene deficient in Werner syndrome was identified by positional cloning to be on chromosome 8 in 1996 and designated WRN." (PMID 39125869, 2024). "They inferred there were at least three distinct clinical types of the disease, with type 1 comprising classical Werner syndrome with pathogenic WRN variants and type 2 group having an earlier age of onset, resembling the LMNA mutant progeroid syndrome." (PMID 37603195, 2024). "This variant in compound heterozygous state with other pathogenic WRN variant has previously been described in individual showing signs of Werner syndrome." (PMID 40060251, 2024). "Background and Aim: Werner syndrome (WS) is an autosomal recessive, adult-onset, progeroid syndrome caused by WRN mutations." (PMID 39625398, 2024). "Werner syndrome (WS) is an autosomal recessive adult-onset progeroid syndrome caused by WRN mutations." (PMID 39625398, 2024). "This review focuses on a very interesting helicase WRN that is deficient in the segmental progeroid disease Werner syndrome (WS)." (PMID 39125869, 2024). "Werner syndrome is associated with biallelic pathogenic variants in the WRN gene (also known as RECQL2), which is located in chromosome 8p12." (PMID 40060251, 2024). "Werner syndrome of premature aging is caused by mutations in the WRN RECQ helicase/exonuclease, which functions in DNA replication, repair, transcription, and telomere maintenance." (PMID 39422615, 2024).
Werner syndrome (continued). "Werner syndrome (WS) is a rare genetic disease in humans, caused by mutations in the WRN gene that encodes a protein containing helicase and exonuclease domains." (PMID 38491858, 2024). "Werner syndrome, another accelerated aging condition, is caused by mutations in the WRN gene, which encodes a helicase enzyme involved in double-strand DNA break repair and genome stability." (PMID 38355681, 2024). "WRN has helicase and exonuclease enzymatic activity, and germline loss of function variants associated with Werner Syndrome are distributed across the gene footprint." (PMID 38587317, 2024). "We report a Lithuanian patient with a homozygous pathogenic variant in the WRN gene that led to Werner syndrome, which was detected in the patient’s late adulthood." (PMID 40060251, 2024). "Werner syndrome is characterized by an autosomal recessive mutation in the WRN gene, and one of the major disease manifestations is cancer predisposition." (PMID 38104125, 2023). "Werner syndrome (WS) is a DNA repair‐related premature ageing syndrome caused by mutations in a RecQ family DNA helicase, WRN." (PMID 37013265, 2023). "Werner syndrome is due to an autosomal recessive mutation in the WRN gene and predisposes patients to malignancy." (PMID 38104125, 2023). "The third RECQ gene, initially known as RECQ3, was isolated during the search for gene mutations underlying Werner’s syndrome and later renamed WRN." (PMID 37626846, 2023). "Variants in this gene are the primary cause of Werner syndrome, a disorder of accelerated ageing, with WRN knockout cell lines presenting with accelerated telomere attrition." (PMID 37239390, 2023). "For example, loss-of-function mutations in Werner syndrome ATP-dependent helicase (WRN) lead to Werner syndrome, a disease that is characterized by premature aging and increased susceptibility to cancer." (PMID 35626643, 2022). "The mutation of WRN is often associated with Werners’ syndrome, an autosomal recessive disorder characterized by the premature onset of a number of age-related diseases." (PMID 35668409, 2022). "Mutation in Werner (WRN) RECQL helicase is associated with premature aging syndrome (Werner syndrome, WS) and predisposition to multiple cancers." (PMID 35582959, 2022). "Werner syndrome, caused by WRN gene mutation, explains a genetic relationship between soft tissue sarcoma, melanoma, and TC." (PMID 36009531, 2022). "Werner Syndrome is an autosomal recessive disorder caused by mutations in the WRN gene, located on chromosome 8p11." (PMID 35782872, 2022). "Identification of biallelic pathogenic WRN variants can help further distinguish a diagnosis of Werner syndrome from other syndromes which can cause features of premature aging." (PMID 35359366, 2022). "Twenty-six years ago, WRN, the gene responsible for the premature aging associated with Werner syndrome (WS), was identified." (PMID 36292687, 2022). "WRN is mutated in Werner syndrome (WS), which is a progeroid syndrome associated with premature aging, type 2 diabetes, osteoporosis, cataracts, graying and loss of hair, skin atrophy, and cancer predisposition." (PMID 35025765, 2022). "Individuals carrying germline mutations in the WRN gene exhibit characteristics of Werner syndrome, including genomic instability, cancer predisposition and accelerated ageing." (PMID 35567571, 2022). "Werner syndrome, also called adulthood-progeria, is caused by autosomal recessive mutations in WRN encoding helicase engaged in DNA repair." (PMID 33917352, 2021). "Deacetylation of H3K9 at telomeric chromatin enables stable association of WRN, the factor that is mutated in Werner syndrome, a human premature aging syndrome." (PMID 33934090, 2021). "Werner syndrome (WRN) is a rare progressive genetic disorder, caused by functional defects in WRN protein and RecQ4L DNA helicase." (PMID 33907225, 2021). "Mutations in the WRN gene give rise to Werner syndrome (WS) and the affected individuals exhibit features of accelerated aging." (PMID 34237055, 2021).
Werner syndrome (continued). "Homozygous truncating variants in the WRN gene cause Werner syndrome (WS; OMIM 277700) manifests, which are characterized by early onset age-associated diseases such as cancer." (PMID 34164337, 2021). "Werner syndrome (WS) is a rare autosomal recessive genetic disorder caused by mutation in the WRN gene." (PMID 34612580, 2021). "The decreased activity of WRN gene promoter is associated with autosomal recessive genetic disease in adults with premature ageing, known as Werner syndrome (WS)." (PMID 33225619, 2021). "Werner Syndrome (WS) is an autosomal recessive disease with genetic instability and cancer predisposition caused by biallelic WRN pathogenic variants." (PMID 33495912, 2021). "In recent studies, the induction of mitophagy and degeneration of NAD+ in Werner syndrome (WS) patients, which is an autosomal recessive accelerated aging disease and caused by mutations in the gene encoding the Werner (WRN) DNA helicase, has been observed." (PMID 34440645, 2021). "Several studies suggest a role for RecQ helicases in telomere maintenance, most prominently a role of human WRN whose absence causes telomere defects and rapid, adult-onset aging in Werner syndrome." (PMID 32085395, 2020). "Alterations in BLM and WRN, the human homologs of Sgs1 result in Bloom and Werner syndromes, respectively, characterized by cancer predisposition and developmental defects." (PMID 31936378, 2020). "Werner’s syndrome (WS) is an autosomal recessive rare genetic disorder characterized by clinical features suggestive of accelerated aging caused by mutation of the WRN gene." (PMID 32680555, 2020). "The canonical examples are Werner Syndrome (WS) and Bloom Syndrome (BS), rare autosomal recessive disorders caused by loss-of-functions mutations in WRN and BLM respectively." (PMID 32367056, 2020). "The Werner Syndrome’s patients carry autosomal recessive WRN RecQ like helicase (WRN) gene mutations on 8p11.1–21.1." (PMID 33218058, 2020). "Down syndrome is caused by trisomy 21, Werner syndrome results from mutations in the Werner syndrome ATP-dependent helicase (WRN), and DKC is a paradigmatic disease for studying the consequences of critical short telomeres." (PMID 32819411, 2020). "The Werner syndrome (WS) is a severe human disease, caused by genetic mutations that lead to loss of WRN protein, and as a result, affected individuals are predisposed to the early-onset of several cancer types." (PMID 32046194, 2020). "Mutations in the RecQ family genes BLM and WRN are linked to rare disorders associated with genome instability, premature ageing and cancer predisposition named Bloom’s syndrome and Werner’s syndrome, respectively." (PMID 33095241, 2020). "A deficiency in WRN leads to Werner syndrome (WS), which is associated with genetic instability, cancer predisposition and premature ageing." (PMID 32283785, 2020). "Werner’s syndrome is an autosomal recessive rare genetic disorder characterized by clinical features suggestive of accelerated aging caused by mutation of the WRN gene." (PMID 32680555, 2020). "Homozygous mutations affecting the RECQ helicases, BLM and WRN, as seen in Bloom Syndrome and Werner Syndrome, respectively, cause defective DNA repair, tumor susceptibility and abnormal development." (PMID 32369918, 2020). "Werner syndrome patients show an increased lifetime risk to develop tumors, pointing to a tumor-suppressive function of WRN." (PMID 30910006, 2019). "Mutations in WRN cause Werner’s syndrome, a premature aging syndrome that also imparts an increased risk of cancer." (PMID 31546714, 2019). "Werner syndrome is an autosomal recessive disorder caused by mutations in the WRN gene on chromosome 8p11.1–21.1." (PMID 31247975, 2019). "Metabolic dysfunction is a primary feature of Werner syndrome (WS), a human premature aging disease caused by mutations in the gene encoding the Werner (WRN) DNA helicase." (PMID 31754102, 2019).